SAMD9L (sterile alpha motif domain containing 9 like)
Diseases named in the same sentence as SAMD9L in open-access papers (continued):
Sharing a sentence is not in itself a finding about the gene and the disease.
Fanconi anemia (2 papers, 2017 to 2022). Fanconi anemia (FA) is a hereditary DNA repair disorder characterized by progressive pancytopenia with bone marrow failure, variable congenital malformations and predisposition to develop hematological or solid tumors. "This included patients with well-known leukemia-predisposing conditions such as Fanconi anemia, Diamond-Blackfan anemia, Shwachman-Diamond syndrome, and SAMD9L germline variants." (PMID 34950979, 2022).
fibromatosis (2 papers, 2007 to 2017). A poorly circumscribed neoplasm arising from the soft tissues. "For instance, SAMD9 is expressed at lower levels in aggressive fibromatosis, while SAMD9L is not." (PMID 17407603, 2007).
gastric cancer (2 papers, 2023 to 2025). A primary or metastatic malignant neoplasm involving the stomach. "Here we show that a mutation of SAMD9L p.T832FS occurred in one allele of patients with gastric cancer and indirectly caused truncation mutation, which may lead to structural and functional abnormalities of SAMD9L protein." (PMID 37158533, 2023). "SAMD9L, which may be associated with gastric cancer, was selected for functional experiments according to literature reports and database analysis." (PMID 37158533, 2023). "The mutation frequency of the SAMD9L gene in gastric cancer samples was 5%, higher than other candidate susceptibility genes, suggesting that it may be closely associated with gastric cancer." (PMID 37158533, 2023). "Therefore, the SAMD9L p.T832fs mutation site may represent a susceptibility factor of this gastric cancer family, which is consistent with literature reports and bioinformatics analysis, and we performed analyses of cell functions." (PMID 37158533, 2023). "Further, the influence of SAMD9L expression levels on the survival of 631 patients with gastric cancer patients was analyzed using a geographic database." (PMID 37158533, 2023). "We found that SAMD9L was low expressed in gastric cancer tissues compared with normal tissues in the TCGA database." (PMID 37158533, 2023). "Therefore, SAMD9L may represent a susceptibility gene of this gastric cancer family." (PMID 37158533, 2023). "The results show that patients with higher SAMD9L expression levels had better survival status, suggesting that SAMD9L may be related to the occurrence and development of gastric cancer." (PMID 37158533, 2023). "Furthermore, it is necessary to further study the effect of SAMD9L overexpression on gastric cancer cells through advanced methods to improve the efficiency of gene expression." (PMID 37158533, 2023).
glioma (2 papers, 2017 to 2023). A benign or malignant brain and spinal cord tumor that arises from glial cells (astrocytes, oligodendrocytes, ependymal cells). "The result suggested that KCNIP, IGFBP2, IL5, and SAMD9L were independent poor prognostic factors for GBM and glioma." (PMID 36762114, 2023).
hepatocellular carcinoma (2 papers, 2018 to 2023). A malignant tumor that arises from hepatocytes. "In particular, somatic mutations have been found in hepatitis B-related hepatocellular carcinomas and inactivation of SAMD9L has been recently correlated with myeloid transformation." (PMID 30211214, 2018).
melanoma (2 papers, 2021 to 2023). A malignant, usually aggressive tumor composed of atypical, neoplastic melanocytes. "SAMD9L is a protein with antiproliferative function and a tumor suppressor role in various types of cancer, recently identified in genetic signatures of pancreas and melanoma tumors." (PMID 37509327, 2023).
metastatic disease (2 papers, 2024 to 2025). "ATP8B1 and SAMD9L mutations may mark metastatic disease, and gender-specific mutations suggest avenues for personalized therapy." (PMID 41590495, 2025). "Notably, significant genetic heterogeneity exists between primary and metastatic tumors, with mutations in ATP8B1 and SAMD9L prominently associated with metastasis." (PMID 41590495, 2025). "Similarly, distinct mutational patterns emerged between primary and metastatic tumors, with DMD and KMT2D more prevalent in primary tumors, while SAMD9L and ATP8B1 were found in metastases." (PMID 41590495, 2025). "While most of our results align with existing studies, the unique identification of mutations such as SAMD9L and ATP8B1 in metastatic tumors and gender-specific enrichment of CDK8 and EPHB2 are less commonly reported and may represent new areas for investigation in personalized therapeutics." (PMID 41590495, 2025). "Analyses of patient data from the Cancer Genome Atlas (TCGA) showed that GIMAP6, SAMD9L, and IL27 are significantly upregulated in metastatic tumors compared to the primary lesions, whereas TAP1 was not differentially expressed in patient samples." (PMID 38719996, 2024).
adrenal hypoplasia (1 paper, 2023). "Meanwhile, adrenal insufficiency due to adrenal hypoplasia is associated with MIRAGE (myelodysplasia, infection, restriction of growth, adrenal hypoplasia, genital phenotypes, and enteropathy) syndrome due to SAMD9/SAMD9L gene mutations." (PMID 37102642, 2023).
allergic asthma (1 paper, 2022). A asthma with a basis in a pathological type I hypersensitivity reaction. "MX1, RSAD2, IFIT1, IFI27, OAS3, and SAMD9L were markedly elevated in HDM-treated mice and positively associated with IL-5, IL-13 and MUC5AC (key mediators of allergic asthma)." (PMID 36211429, 2022). "Furthermore, MX1, RSAD2, IFIT1, IFI27, OAS3, and SAMD9L levels correlated positively with IL-5, IL-13, and MUC5AC levels, which are the key mediators of allergic asthma." (PMID 36211429, 2022).
autoinflammatory syndrome (1 paper, 2025). A group of disorders of the innate immune system characterized by attacks of seemingly unprovoked inflammation without significant levels of either autoantibodies or autoreactive T cells more characteristic of autoimmune disease. "Recent studies have linked SAMD9L mutations to severe autoinflammatory syndromes, characterized by ILD, elevated inflammatory markers, cytopenias, and immune dysregulation, which closely resemble clinical and immunological features seen in SSc-ILD." (PMID 40843700, 2025).
Dias-Logan syndrome (1 paper, 2021). Any BAFopathy in which the cause of the disease is a mutation in the BCL11A gene.
Flavivirus Infections (1 paper, 2025). Infections with viruses of the genus FLAVIVIRUS, family FLAVIVIRIDAE. "In this study, we investigated one of these proteins, called SAMD9L, and found that it plays a key role in protecting human cells from flavivirus infection." (PMID 41359666, 2025). "To investigate the physiological antiviral role of SAMD9L in IFN-mediated resistance to flavivirus infection in myeloid cells, we conducted knockdown experiments targeting endogenous IFN-induced SAMD9L." (PMID 41359666, 2025). "Furthermore, its knockdown in human myeloid cells, including microglial cells and primary macrophages, impaired the antiviral activity of type I interferon, identifying SAMD9L as a key antiviral ISG in primary target cells of flavivirus infection." (PMID 41359666, 2025).
Friedreich ataxia (1 paper, 2023). An inherited condition that affects the nervous system and causes movement problems. "Eleven participants with other NDDs were also recruited, comprising five AD, three PSP, and three with hereditary ataxias (two with Friedreich ataxia and one with a mutation in the SAMD9L gene)." (PMID 37891183, 2023).
lymphopenia (1 paper, 2022). Reduction in the number of lymphocytes. "Genomic and phenotypic analyses recapitulated many of the hematopoietic cellular phenotypes observed in patients with SAMD9 or SAMD9L mutations, including lymphopenia, and pinpointed TGF-β as a potential targetable pathway." (PMID 36074606, 2022). "We also observed a concomitant increase in relative percentages of myeloid precursors in Samd9l-Mut mice, especially after inflammation, a potential response to the associated lymphopenia, a process known as emergency granulopoiesis." (PMID 36074606, 2022). "In fact, this is not completely surprising, as clinical reports have shown that lymphopenia in general, and particularly B cell ablations, are observed in BMF syndromes, including patients with mutant SAMD9L." (PMID 36074606, 2022).
pulmonary TB (1 paper, 2022). "The top performing single biomarkers for pulmonary TB versus controls were CALCOCO2, SAMD9L, GBP1, IFITM3, IFIT3 and SNX10." (PMID 35720382, 2022).
rheumatoid arthritis (1 paper, 2017). A chronic, systemic autoimmune disorder characterized by inflammation in the synovial membranes and articular surfaces. "Thus, if SAMD9L is specifically expressed by FLS in synovial membrane and the gene has a proliferation depressing effect, the expression of the gene in FLS from joints with inflammatory arthritis or rheumatoid arthritis should be investigated." (PMID 28410619, 2017).
Sepsis (1 paper, 2018). Sepsis is defined as life-threatening organ dysfunction caused by a dysregulated host response to infection. "Collectively, FFAR2, MAPK14, LTB, SAMD9L shown dysregulation in all three studies, indicating their roles at both cellular and system-level responses to sepsis." (PMID 30086151, 2018).
Sjogren syndrome (1 paper, 2025). An autoimmune disorder in which immune cells attack and destroy the glands that produce tears and saliva. "In our study, half of the SSc patients with likely pathogenic variants in the SAMD9L gene (four out of eight) suffered from Sjogren’s syndrome, while two had a compound heterozygous state." (PMID 41283471, 2025). "A previous study identified a significant association between SAMD9L expression and immune cell infiltration, suggesting its potential role as a biomarker in Sjögren’s syndrome." (PMID 41283471, 2025).
Tremor (1 paper, 2025). An unintentional, oscillating to-and-fro muscle movement about a joint axis. "Progressive tremor was associated with genes CACNA1A, CSTB, and SAMD9L." (PMID 40326640, 2025).
tuberculosis (1 paper, 2022). A chronic, recurrent infection caused by the bacterium Mycobacterium tuberculosis. "Therefore, the function of SAMD9L in tuberculosis was preliminarily explored in this paper." (PMID 35388602, 2022).
tumor (17 papers, 2007 to 2025). "SAMD9, like SAMD9L, is involved in control of cell proliferation and functions as a tumor suppressor in some cancers." (PMID 29535429, 2018). "The function of this gene is not well characterized; however, evidence has accumulated supporting the role of SAMD9L in cell proliferation and tumor suppression." (PMID 30211214, 2018). "Surprisingly, germline variants in SAMD9 or SAMD9L were present in 17% of primary MDS patients, and these variants were routinely lost in the tumor cells by chromosomal deletions (e.g., monosomy 7) or copy number neutral loss of heterozygosity (CN-LOH)." (PMID 29146900, 2017). "A recent study has investigated proliferation depressing effects of SAMD9L, and SAMD9L expression was reduced in tumours." (PMID 28410619, 2017). "SAMD9 and SAMD9L are expressed ubiquitously in human tissues, but they are expression at lower levels in neoplasia." (PMID 17407603, 2007). "Furthermore, Kaplan–Meier patient survival was positively correlated with the expression level of SAMD9L, supporting that SAMD9L is a tumor suppressor." (PMID 37158533, 2023). "Among them, SAMD9L regulates cell proliferation as a tumor suppressor gene." (PMID 37158533, 2023). "This supports the hypothesis proposed that primary SAMD9L mutations do not lead per se to tumour cell proliferation, but that a secondary genomic event consisting of either Chromosome 7 monosomy or somatic mutations in driver genes would be needed to predispose to MDS and haematological malignancy." (PMID 35310830, 2022). "SAMD9 and SAMD9L are likely to act as growth suppressors, and overexpression of SAMD9 suppresses tumor progression in non–small cell lung cancer cells." (PMID 28346228, 2017). "The significantly regulated genes identified in both KYSE150 and KYSE410 cells were found to be involved in cell adhesion (PCDH family genes, CLDN1, CNTN1), cell apoptosis (MAPK10/JNK3, PYCARD), tumor suppression (TUSC3, SAMD9L) and immunity regulation (IFNL3)." (PMID 32089740, 2020). "The knockouts in tumor cell lines from various tissues and the normal human foreskin fibroblasts showed that both SAMD9 and SAMD9L, when sufficiently expressed, could inhibit vK1L-C7L- replication." (PMID 29447249, 2018). "Mouse is one of the mammalian species that have lost SAMD9 gene, and a previous study suggested that mouse SAMD9L was not a functional paralog of human SAMD9 in terms of the tumor suppressor function." (PMID 29447249, 2018).
infection (8 papers, 2014 to 2025). The state of being infected such as from the introduction of a foreign agent such as serum, vaccine, antigenic substance or organism. "To test whether SAMD9L haploinsufficiency would increase susceptibility to vK1L-C7L- infection, we infected SAMD9L+/+ and SAMD9L+/- mice with the highest dosage of vK1L-C7L- we could reasonably obtain (107 PFU in 20 μl)." (PMID 29447249, 2018). "In order to comprehensively explore the expression level of SAMD9L after Mtb infection, we constructed a mouse model of Mtb infection and measured the expression level of lung and spleen tissues after infection." (PMID 35388602, 2022). "In fact, SAMD9 and SAMD9L are host restriction factors activated as a defensive mechanism in response to infection with viruses such as vaccinia, myxoma, and rhinovirus." (PMID 36074606, 2022). "In contrast to their SAMD9L+/+ and SAMD9L+/- littermates, all SAMD9L-/- mice lost close to 25% of body weight by day 5 post infection and had to be euthanized." (PMID 29447249, 2018). "Intranasal infection of SAMD9L+/+ and SAMD9L+/- mice with 106 plaque-forming unit (PFU) of vK1L-C7L- did not cause any disease symptom or sustained body weight loss, similar to the mock infection." (PMID 29447249, 2018). "Within the locus we also identified host genes whose expression increased (Samd9l, Asns, Gpr85, and Tfpi2) or decreased (Pon1, Hepacam2, Tmem106b, and Pppr9a1) 2-fold (P < 0.05) 72 hours after infection with H5N1 IAV in D2, B6 or both mouse strains." (PMID 25418976, 2014). "Interestingly, even in the absence of exogenous IFN-I, SAMD9L knockdown resulted in enhanced WNV replication, suggesting that endogenously produced IFN-I during infection induces sufficient SAMD9L expression to exert partial antiviral effects (left)." (PMID 41359666, 2025). "Other studies have shown SAMD9L to be upregulated in active TB as compared to LTBI infection, it may therefore play a role in intracellular uptake and trafficking of TB bacilli." (PMID 35720382, 2022). "Our results showed that SAMD9L was up‐regulated in RAW264.7 and BMDM after Mtb infection, and its expression reached the highest level after 24 h of infection." (PMID 35388602, 2022). "Here, we show that SAMD9L functions similarly to SAMD9 as a restriction factor and that the two paralogs form a critical host barrier that poxviruses must overcome to establish infection." (PMID 29447249, 2018). "Interestingly, SAMD9L knockdown also led to increased WNV replication even in the absence of exogenous IFN-I, suggesting that infection-induced, endogenous IFN-I is sufficient to upregulate SAMD9L expression to levels that can restrict WNV replication." (PMID 41359666, 2025).
cancer (5 papers, 2021 to 2025). A tumor composed of atypical neoplastic, often pleomorphic cells that invade other tissues. "A few genes on chromosome 7 that may play a crucial role in the disease pathogenesis and phenotype of cancers are EZH2, KMT2A, SAMD9, SAMD9L, and CUX1." (PMID 39463522, 2024).
haematologic disorders (2 papers, 2022 to 2025). "Identification of SAMD9L pathogenic variants is particularly important as there is a risk of hematological malignancies in carriers of pathogenic SAMD9L variants even if the magnitude of the increase in risk for myelodysplastic disorders is still unclear." (PMID 36553623, 2022).
genetic disorders (1 paper, 2025). "Most of these genetic disorders arise from germline gain-of-function mutations in SAMD9 or SAMD9L, which lead to excessive translational repression, thus disrupting normal cellular growth and functions." (PMID 41359666, 2025).
SAMD9L also shares sentences with these, for which no sentence is quoted: acute myeloid leukemia (3 papers); Autoimmunity (2); bone marrow failure (2); monosomy (2); platelet disorder (2); aplastic anemia (1); asthma (1); cerebellar ataxia (1); demyelinating peripheral neuropathy (1); Diamond-Blackfan anemia (1); Graves disease (1); hepatitis B- (1); hereditary ataxia (1); juvenile myelomonocytic leukemia (1); leukemia (1); lymphoma (1); mesothelioma (1); myeloid leukemia (1); myxoma (1); Noonan-like syndrome (1); osteoarthritis (1); pancreatic cancer (1); peripheral neuropathy (1); primary immunodeficiency (1); progressive ataxia (1); pulmonary arterial hypertension (1); renal carcinoma (1); Sensory neuropathy (1); Shwachman-Diamond syndrome (1).